PKD1P4 (polycystin 1, transient receptor potential channel interacting pseudogene 4)
Synonyms: HG4
Gene: Transcribed unprocessed pseudogene on chromosome 16 (18,334,400 to 18,352,476, reverse strand). Ensembl gene ENSG00000205746.
Diseases named in the same sentence as PKD1P4 in open-access papers:
PKD1P4 is named in the same sentence as 4 diseases in open-access papers, as found by Europe PMC text mining. Sharing a sentence is not in itself a finding about the gene and the disease.
PKD1P4 shares sentences with these, for which no sentence is quoted: cancer (1 paper); COVID-19 (1); infection (1); renal fibrosis (1).